CD4 (CD4 molecule)
Diseases named in the same sentence as CD4 in open-access papers (continued):
Sharing a sentence is not in itself a finding about the gene and the disease.
Stroke (continued). "The results showed a correlation of the surface expression of CD137 on CD4+ T cells and levels of plasma sCD137 with NIHSS (r = 0.7167, P < 0.0001 and r = 0.7119, P = 0.0137) and infarct volume (r = 0.6207, P = 0.0006 and r = 0.7072, P < 0.0001) in stroke patients." (PMID 29697202, 2018). "CD4 + CD28− cells and WBC may be involved in POD induced by stroke." (PMID 29137628, 2017). "In the sham group without stroke, few CD4 cells could be detected (data not shown); thus, no CD4 T cells from the sham group could be used for gene expression measurements." (PMID 27609334, 2016). "Third, a stroke-induced reduction in the CD3+CD4+/CD3+CD8+ T cell ratio was absent in IFN-βKO mice." (PMID 26581581, 2015). "RTL treatment significantly decreased the frequency of CD4+, CD8+, and CD3+ T cells and increased B cells in the spleen of young mice following MCAO suggesting that in young mice, RTL treatment counteracts changes in immune cell subsets that occur in the spleen after stroke." (PMID 25309326, 2014). "Recent studies have reported that CD4+ Tregs play a protective role against damage following stroke, while others demonstrate Tregs as harmful promoters of neurodegeneration or find that Tregs do not influence stroke." (PMID 25309326, 2014). "The frequency of CD4+ Foxp3+ regulatory cells in the spleen increases after MCAO although there are contradicting data on whether CD4+ regulatory T cells diminish or exacerbate stroke related neuronal damage." (PMID 25309326, 2014). "Furthermore, it has been reported that FoxP3+CD25+CD4+ Tregs may be a facilitator for Cocaine-and-amphetamine-regulated-transcript- (CART-) mediated neuroprotection after stroke." (PMID 23983771, 2013). "Moreover, intravenous albumin administration reduced Toll-like receptor 4 expression but significantly increased FoxP3+CD25+CD4+ Tregs expression levels and elevated IL-10 and TGF-β1 production, eventually conferring neuroprotective effects during postischemic stroke treatment." (PMID 23983771, 2013). "Advancing our understanding of FoxP3+CD25+CD4+ Tregs and utilizing FoxP3+CD25+CD4+ Tregs to selectively suppress the deleterious effects of excessive brain immunoreaction after stroke may provide novel therapeutic approaches for stroke patients." (PMID 23983771, 2013). "The results showed that low levels of CD4+FoxP3+ Treg cells but not CD4+CD25+FoxP3+ Treg cells were associated with an increased risk for myocardial infraction, and neither CD4+ FoxP3+ Treg cells nor CD4+CD25+FoxP3+ Treg cells were associated with stroke." (PMID 24385687, 2013). "Moreover, the CD4+/CD8+ ratio was never used as a marker of stroke patients’ status." (PMID 40342517, 2025). "More interestingly, intraplaque CD4+ T cells number was heightened in patients with symptomatic disease (recent stroke or transient ischemic attack) compared to asymptomatic disease (no recent stroke), suggesting that CD4+ T cell subsets play a critical role in plaque stability." (PMID 36552564, 2022). "Unlike CD8+ T cells, however, CD4+ T cells showed different pattern of infiltration, rising prominently 3 days after stroke, and then decreasing 7 days after stroke, to the point that only a small proportion of the gated cells were detectable as CD4+ T cells 14 days after stroke." (PMID 30444079, 2019). "Interestingly, the possibility that endogenous induction of Tregs by BMDCs within the bone marrow cannot be ruled out as a small population (< 0.5%) of CD4+CD25+Foxp3+ Tregs constitute the bone marrow stem cell population which was shown to be neuroprotective in a rat model of experimental stroke." (PMID 29783988, 2018). "The difference seen between our and their results might be due to the fact that different markers were used for the detection of Tregs (in our study, this subset was described as CD4+ CD25high cells, and FoxP3 was not applied) and that the severity of stroke was different in the two investigations." (PMID 24597828, 2014).
Stroke (continued). "In the stroke cohort, absolute CD25+ CD4+ T cell counts were not significantly altered over the study period." (PMID 41373643, 2025). "The absolute number and percentage of CD4+ and CD8+ T cells in a population of CD3+ T cells neither differ in comparison to the control group nor change with the time after stroke." (PMID 40342517, 2025). "On the other hand, a negative correlation was noted between the percentage of CD4+ T cells on D1 and the serum level of CRP on D10 after stroke." (PMID 40342517, 2025). "A negative correlation was noted between the percentage of CD4+ T cells on D1 and the serum CRP level on D10 after stroke." (PMID 40342517, 2025). "Similar reductions in infarct size were observed in our studies and others when CD4+ or CD8+T cells were absent, as measured 1–4 days post-stroke." (PMID 38334672, 2024). "We found that high-dose vitamin D supplements increased overall CD3+ percentage and CD4+ percentage and cell counts, but did not affect CD8+ percentage and count in overweight and obese Black individuals living inside the Stroke Belt." (PMID 36235575, 2022). "Third, although stroke did not significantly alter the phosphorylation of PRAS40 between the Akt and the mTOR pathways, CD4 T cell deficit results in significantly higher levels of P-PRAS40 at 24 h compared with WT mice." (PMID 32832192, 2018). "Evidence suggests that CD4+ T and CD8+ T lymphocytes, but not B lymphocytes, contribute to the inflammatory thrombosis, brain injury, and neurological deficit in experimental stroke models." (PMID 29246244, 2017). "The ratios of CD4+/CD8+ and Foxp3+/Foxp3− in CD4+ cells were not altered in stroke animals compared with naïve and sham surgery rats." (PMID 23555048, 2013). "We showed that the lack of CD4+, CD8+ T cells, or total T cells, resulted in smaller infarction measured 2 d post-stroke." (PMID 23555048, 2013). "Notably, following stroke induction, the population of double-negative T cells (DNTs) (CD3+, CD4-, CD8-, NKG7-) showed significant variation." (PMID 40018035, 2025). "However, the results from flow cytometry in this study show that CD4+ T cells and CD8+ T cells were decreased in patients who had a stroke, which did not align with the result in a study using scRNA-seq." (PMID 39633897, 2024). "There were no significant changes in monocytes CD4+ cells, CD8+ cells, and NK1.1+ cells in blood of recipient stroke mice among plasma from naive donor group, whole blood from naive donor group, and whole blood from the stroke mice group." (PMID 32843630, 2020). "Thus, stroke-induced reductions in splenocyte numbers and CD3+CD4+/CD3+CD8+ T cell ratio were absent in IFN-βKO mice." (PMID 26581581, 2015). "The lack of a substantial number of severe stroke patients in this study, however, may deceptively lead to overlooking the effects of stroke severity on the number of FoxP3+CD25+CD4+ Tregs." (PMID 23983771, 2013). "The peripheral blood leukocyte count (WBC), the absolute number, and the percentage of CD4+ and CD8+ T cells in the population of CD3+ lymphocytes or CD4−CD8− T cells in the population of CD3+ lymphocytes did not change significantly during the time after the stroke." (PMID 40342517, 2025).
pneumonia (203 papers, 2007 to 2026). An acute, acute and chronic, or chronic inflammation focally or diffusely affecting the lung parenchyma, caused by an infection in one or both of the lungs (by bacteria, viruses, fungi, or mycoplasma.). "Impairments in adaptive immunity, particularly defects in CD4+ T cell function, are strongly associated with the development of severe Pneumocystis pneumonia (PCP) in humans and a wide range of mammalian species." (PMID 42042334, 2026). "The observed changes in the content of CD4+FoxP3+ lymphocytes in acute pneumonia suggests a possible association with the activity of anti-inflammatory cytokines, primarily interleukin-4." (PMID 41463029, 2025). "A total of 41 individuals with HIV infection were enrolled in this study, including 21 patients with Mpox-associated pneumonia and CD4+ T-cell counts <200/μL, and 20 HIV/Mpox co-infected individuals without pulmonary involvement who served as controls." (PMID 41356465, 2025). "The study showed that the development of acute pneumonia is associated with marked changes in the regulatory mechanisms of the immune response, especially for CD4+FoxP3+ T cells and cytokines involved in maintaining immune homeostasis." (PMID 41463029, 2025). "By moving beyond a simple binary classification, we sought to establish CD4+ T cells count as a key variable for optimizing initial empirical antimicrobial therapy and refining diagnostic pathways in severe pneumonia." (PMID 41488483, 2025). "The results showed that sFGL2 > 70.58 ng/ml, as well as cell counts of CD3+ T cells, CD8+ T cells, CD4+ T cells, and lymphocytes, were risk factors for pneumonia in COVID‐19 KTRs." (PMID 41146434, 2025). "For pneumonia caused by other pathogens, regulatory CD4+CD25+ T cells were found to suppress respiratory inflammation by promoting IL-17 and IFN-γ responses in a mouse model of mycoplasma pneumonia." (PMID 39114653, 2024). "In individuals diagnosed with HIV, the risk of developing pneumonia is 25 times higher than in the general population, increasing with decreasing CD4 count." (PMID 38543710, 2024). "The risk of developing pneumonia among children presented with a CD4 cell count below the threshold was 2.71 times [AHR: 2.71 (95% CI: 1.37, 5.35)], higher as compared to those children with a CD4 count above the threshold." (PMID 39232814, 2024). "In a mouse lung infection model with pneumonia virus, Fcgr1 expression in inflammatory type 2 dendritic cells was linked with superior CD4+ T-cell polarization as well as antigen presentation to CD8+ T cells." (PMID 39425188, 2024). "For example, early activation of Tregs during Staphylococcus aureus sepsis was found to induce CD4+ T cell impairment and increase susceptibility to secondary pneumonia." (PMID 37033939, 2023). "Pneumonia risk is higher in HIV infection with lower CD4 + T cell count, and several pathogens cause pneumonia." (PMID 35130846, 2022). "Additional experiments demonstrated that B cells, CD4+ and IL-17 were each necessary for protection against S. pneumoniae pneumonia caused by the 19F strain." (PMID 30881363, 2019). "Diaz reported that cigarette smoking, IDU, low CD4 cell count, and previous history of pneumonia were associated with increased respiratory symptoms." (PMID 19621086, 2009). "Antiretroviral use was highly protective and, consistent with previous observations, a low CD4 cell count was significantly associated with pneumonia risk." (PMID 19340321, 2008). "CD4 cell count was inversely associated with pneumonia incidence (for each 100 CD4 cell count increase the incidence rate decreased by 16% (IRR = 0.84)." (PMID 19340321, 2008). "In the interim, three mothers died of cryptococcal meningitis, pneumonia and an unknown cause; all had virological failure and two of three who died had CD4 counts <200 in 2013." (PMID 39792915, 2025).
pneumonia (continued). "Furthermore, in the pneumonia model infected with the colistin-susceptible AbCS01 strain, both sulbactam therapy and treatment with memory CD4+ T and B cells increased survival rates compared with the untreated control animals (+80%, +70%, and +80%, p < 0.05)." (PMID 39408879, 2024). "This shows that SARS-CoV-2 may mainly attack lymphocytes in the body, which can cause the reduction of CD4 + T lymphocytes, resulting in decreased immune function and infection, and severe cases of severe pneumonia." (PMID 32364527, 2020). "Therefore, hNE leakage-induced cleavage of HLA molecules may inhibit CD4+ T-cell activation, downregulate cytokine production, and exacerbate severe pneumonia associated with ALI and ARDS." (PMID 33510372, 2021). "These guidelines also emphasise that Toxoplasma-seropositive patients with CD4+ counts of <100 cells/μL should receive prescribed, routine treatment with trimethoprim + sulfamethoxazole or atovaquone to prevent toxoplasmic encephalitis and Pneumocystis jirovecii-associated pneumonia." (PMID 34683355, 2021). "In addition, there is some evidence that Th17 cells actually might be deleterious during S. pneumoniae pneumonia, possibly explaining why we found CD4 depletion was associated with a trend towards fewer bacteria in the blood at 18 h." (PMID 22003400, 2011). "The MXF-19 complex ((o-Fph)PPhβCD) demonstrated immunomodulatory effects both in metal-induced aseptic inflammation and in the acute pneumonia model, leading to normalization of CD4+ and CD4+CD25+ populations and a reduction in CD4+CD25+FoxP3+ T cells." (PMID 41463029, 2025). "MXF-22 has a pronounced immunomodulatory effect, contributing to the restoration of the function of CD4+ FoxP3+ regulatory T cells in acute pneumonia." (PMID 41463029, 2025). "Our results suggest that monitoring lymphocyte subpopulations, specifically CD4+ count, has clinical significance in assessing the severity of pneumonia." (PMID 39858309, 2025). "Immunofluorescence staining analysis showed that CD11c+ CD14+ DCs were spatially located near CD4+ T cells in the lungs of pneumonia patients." (PMID 40789072, 2025). "In animals with the acute pneumonia model, there was a decrease in the number of CD4+ FoxP3+ cells and a violation of the ratio of anti-inflammatory cytokines, including IL-4 and TGF-β." (PMID 41463029, 2025). "In particular, she had received BCG vaccination, developed locoregional BCGitis, and ultimately died of cytomegalovirus (CMV) pneumonia, highlighting the profound impairment of CD4+-mediated activation and antiviral responses in the absence of MHC II." (PMID 41376631, 2025). "Biological evaluation in a rat model of acute pneumonia demonstrated that the complex exerts significant immunomodulatory effects, restoring CD4+ and CD4+CD25+ T-cell populations while reducing immunosuppressive CD4+CD25+FoxP3+ regulatory T cells." (PMID 40649259, 2025). "In rats with acute pneumonia, there was a significant decrease in the content of CD4+CD25+ lymphocytes relative to the control group." (PMID 41463029, 2025). "In the specific context of pneumonia, CD4+ regulatory T cells (Tregs), characterized by the expression of CD25+ and FoxP3+, serve a central function in suppressing pathological immune activation and promoting tissue repair." (PMID 40649259, 2025). "In conclusion, r-hGH increased the number of the CD4+ T cells in severe neurosurgical patients, down-regulated inflammatory mediators, shortened the cure time of pneumonia and intracranial infection, and improved the prognosis of patients." (PMID 39792837, 2025). "This study was designed to evaluate the complex’s immunomodulatory potential in a rat model of acute pneumonia, with a particular focus on CD4+ T-cell subpopulations, including Tregs." (PMID 40649259, 2025).
pneumonia (continued). "The change in the proportion of CD4+ FoxP3+ cells makes it possible to more accurately characterize the degree of activation and regulatory potential of the immune system in acute pneumonia and under the influence of the studied drugs." (PMID 41463029, 2025). "Acute pneumonia is frequently accompanied by immune suppression, particularly affecting T-cell subsets, such as CD4+, CD4+CD25+, and CD4+CD25+FoxP3+, which are critical for immune regulation." (PMID 40649259, 2025). "Our current study has identified a Tfh cell subset (CD4+FoxP3-CXCR5+ cells) that is increased in progressive pneumonia and K.p-positive pneumonia." (PMID 39911385, 2025). "Our results showed that r-hGH treatment was effective in shortening the cure time of pneumonia and intracranial infections in severe neurosurgical patients and increasing CD4+ T cell counts." (PMID 39792837, 2025). "To provide a more comprehensive assessment of T-cell immunity in acute pneumonia, we additionally evaluated the population of CD4+CD25+ lymphocytes, which reflects regulatory T-cell (Treg) activity and their role in limiting the inflammatory response." (PMID 41463029, 2025). "Previous research has revealed that HIV-infected individuals with a lower CD4+ T-cell count and CD4+/CD8+ ratio are prone to pneumonia." (PMID 39224706, 2024). "In individuals diagnosed with HIV, the HIV/pneumonia group had the lowest CD4 count (median 56 vs. 414 cells/μL), and only 38% of this group received antiretrovirals vs. 73% in the HIV group." (PMID 38543710, 2024). "CD4+ levels were significantly lower in DAD pneumonia (49.4% ± 15.7%) compared to ARDS (66.4% ± 19.3%) and thrombosis (70.2% ± 28.9%) (p < 0.05)." (PMID 40190436, 2024). "Children presented with a CD4 cell count below the threshold were increased 2.71 times probability to develop pneumonia as compared to their counterparts." (PMID 39232814, 2024). "Cell-type deconvolution of preoperative RNA-sequencing revealed elevated S100A8/9-high neutrophils alongside reduced naïve CD4 T-cells in those later developing pneumonia." (PMID 37497667, 2024). "In the pneumonia model by AbCR17, a single dose of memory B or CD4+ T cells also reduced the bacterial load in the lungs compared with both antibiotic groups and was more efficacious than tigecycline in terms of blood clearance." (PMID 39408879, 2024). "With respect to increased survival, treatment with a single dose of memory B or CD4+ T cells was as effective as a three-day treatment with sulbactam at pharmacodynamically optimized doses in the pneumonia murine model for both strains." (PMID 39408879, 2024). "Patients treated with BTK inhibitors have high rates of infectious complications, including pneumonia, even with preserved CD‐4 cell counts." (PMID 37081733, 2023). "Meanwhile, the frequency of CD8+ T cells and CD4-CD8- T cells elevated, while CD4+ T cells decreased obviously in the lungs of mice after pneumonia." (PMID 37490715, 2023). "Next, we compared SSTI- and pneumonia-primed CD4+ T cell responses in the lung 7 days after secondary pneumonia." (PMID 35983063, 2022). "Each of these immunopathology biomarkers (sTREM-1, alveolar macrophage, IL-6, IL-17, CD4 T-cells, Tregs, SP-A or Caspase-3) has been studied independently to mediate local inflammatory responses in severe pneumonia patients." (PMID 35786088, 2022). "Together, these results demonstrate that SSTI and pneumonia each resulted in expansion of local effector CD4+ T cells, possibly even moreso following pneumonia." (PMID 35983063, 2022). "Despite the differences in protection, SSTI and pneumonia each elicited early local expansion of effector CD4+ T cell subsets (day 7 post-infection)." (PMID 35983063, 2022). "We next investigated systemic responses by quantifying Th1, Th17, Treg, and Tfh CD4+ T cells in the spleen 7 days after primary pneumonia or SSTI." (PMID 35983063, 2022).